AGA (aspartylglucosaminidase)
Description:
Cleaves the GlcNAc-Asn bond which joins oligosaccharides to the peptide of asparagine-linked glycoproteins.
Synonyms: ASRG; AGU; GA
Tractability: Small molecule: a structure with a bound ligand is known. Antibody: its Gene Ontology location is reachable by antibodies, with high confidence; UniProt predicts a signal peptide or a membrane-spanning region. PROTAC: ubiquitination databases record sites on it; its protein half-life has been measured.
Gene: Protein-coding gene on chromosome 4 (177,430,774 to 177,442,444, reverse strand). Ensembl gene ENSG00000038002.
Subcellular location: Lysosome
Pathways (Reactome):
Immune System: Neutrophil degranulation
Gene Ontology:
Molecular function: N4-(beta-N-acetylglucosaminyl)-L-asparaginase activity; protein binding; hydrolase activity
Biological process: protein deglycosylation
Cellular component: endoplasmic reticulum; extracellular region; lysosome; azurophil granule lumen; cytoplasm
Genetic constraint (gnomAD): Loss-of-function variants: 21 observed, 32.24 expected, observed/expected ratio (o/e) 0.65, 90% interval 0.46 to 0.94. The upper end of that interval is the gene's LOEUF score, 0.94, which puts it in group 3 of 6, group 1 being the genes least tolerant of losing a copy. Missense variants: 404 observed, 410.55 expected, observed/expected ratio (o/e) 0.98, 90% interval 0.91 to 1.07. Synonymous variants: 137 observed, 138.73 expected, observed/expected ratio (o/e) 0.99, 90% interval 0.86 to 1.14.
Gene-disease validity (ClinGen):
ClinGen rates the evidence that AGA causes each of these diseases.
aspartylglucosaminuria (autosomal recessive): Definitive. Aspartylglycosaminuria (AGU) is an autosomal recessive lysosomal storage disease belonging to the oligosaccharidosis group (also called glycoproteinosis).
Homologues: Orthologues: chimpanzee AGA (99% identical), macaque AGA (95% identical), rabbit AGA (85% identical), pig AGA (84% identical), mouse Aga (82% identical), rat Aga (82% identical), guinea pig AGA (80% identical), tropical clawed frog aga (64% identical), dog AGA (62% identical), zebrafish aga (61% identical), Drosophila melanogaster CG1827 (54% identical), Caenorhabditis elegans R04B3.2 (47% identical), and 2 more. Paralogues in human: ASRGL1 (25% identical), TASP1 (24% identical).
Diseases named in the same sentence as AGA in open-access papers:
AGA is named in the same sentence as 34 diseases in open-access papers, as found by Europe PMC text mining. Sharing a sentence is not in itself a finding about the gene and the disease. The quoted sentences say what the papers report.
aspartylglucosaminuria (15 papers, 2016 to 2025). "Aspartylglucosaminuria (AGU) is a lysosomal storage disorder caused by the deficiency of the lysosomal hydrolase aspartylglucosaminidase (AGA)." (PMID 36982794, 2023). "Mutations in the AGA gene are known to cause the lysosomal storage disease aspartylglycosaminuria, eventually resulting in neurodegeneration." (PMID 36344807, 2022). "To test the suitability of the SLC35A1 knockout cells for a potency assay, we used an AAV9 vector (AAV9/AGA) that carries the optimized human AGA gene coding for aspartylglucosaminidase (AGA) that is deficient in aspartylglucosaminuria (AGU)." (PMID 34069698, 2021). "Aspartylglucosaminidase (AGA) is a low-abundance intracellular enzyme that plays a key role in the last stage of glycoproteins degradation, and whose deficiency leads to human aspartylglucosaminuria, a lysosomal storage disease." (PMID 28742131, 2017). "As a specific example, a variant in the AGA gene (c.488G>C; MAFFinns=0.0096; MAFBritons=0) is enriched 28-fold in Finns and is associated with aspartylglucosaminuria (OMIM #208400)." (PMID 28145424, 2017). "In eukaryotes, AGA is described as a soluble lysosomal amidase whose genetic deficiencies in human causes aspartylglucosaminuria." (PMID 28742131, 2017). "This change would be predicted to result in a truncated protein that is most likely highly unstable, in accordance with the effects described for AGA gene mutations that result in aspartylglucosaminuria." (PMID 27983621, 2016). "The deficiency of aspartylglucosaminidase (AGA) results in aspartylglucosaminuria (AGU), a lysosomal storage disorder characterized by glycoasparagine accumulation." (PMID 39469623, 2024). "Mutations in the AGA gene result in aspartylglucosaminuria (AGU, OMIM 208400), a lysosomal storage disorder that is characterized by progressive loss of intellectual capabilities and some skeletal abnormalities." (PMID 28346360, 2017). "Aspartylglucosaminuria (AGU) is a lysosomal storage disorder that is caused by genetic deficiency of the enzyme aspartylglucosaminidase (AGA) which is involved in glycoprotein degradation." (PMID 27876883, 2016). "Aspartylglucosaminuria (AGU, OMIM 208400) is a rare lysosomal storage disorder caused by the deficiency of aspartylglucosaminidase (AGA), a hydrolase involved in lysosomal degradation of N-glycosylated proteins." (PMID 36358448, 2022). "Aspartylglucosaminuria (AGU, OMIM 208400) is a rare lysosomal storage disorder that is caused by a deficiency of the aspartylglucosaminidase (AGA; N4-(β-N-acetylglucosaminyl)-L-asparaginase, EC 3.5.1.26) enzyme." (PMID 34831035, 2021). "Aspartylglucosaminuria (AGU; OMIM 208400) is a recessive lysosomal storage disorder caused by mutations in the gene coding for aspartylglucosaminidase [AGA, N4-(β-N-Acetylglucosaminyl)-L-Asparaginase, EC 3.5.1.26]." (PMID 27876883, 2016). "Aspartylglucosaminuria (AGU, OMIM 208400) is a neurodevelopmental disease caused by the deficiency of a lysosomal hydrolase, aspartylglucosaminidase (AGA, EC 3.5.1.26)." (PMID 36982794, 2023). "Codon optimization of aspartylglucosaminidase (AGA) led to a 2.5 to 5-fold increase in expression in HEK293 and HeLa cells, supporting its utility for enzyme replacement therapy and gene therapy in aspartylglucosaminuria." (PMID 40806226, 2025). "Aspartylglucosaminuria (AGU) is a lysosomal storage disorder caused by a deficiency of the AGA gene and the resulting lack of activity of the aspartylglucosaminidase (AGA) enzyme." (PMID 34069698, 2021).
lysosomal storage disorder (11 papers, 2015 to 2024). "AGU [Online Mendelian Inheritance in Man (OMIM) 208400] is a neuropediatric lysosomal storage disease that results from pathogenic variants in the AGA gene." (PMID 36285626, 2022). "Like other lysosomal enzymes, the deficiency of AGA leads to lysosomal storage disorder and AGA mutation was suggested to be weakly associated with chronic arthritis." (PMID 26509176, 2015).
Fabry disease (2 papers, 2020 to 2023). Fabry disease (FD) is a progressive, inherited, multisystemic lysosomal storage disease characterized by specific neurological, cutaneous, renal, cardiovascular, cochleo-vestibular and cerebrovascular manifestations. "Fabry disease (FD) is an X-linked lysosomal disorder arising from molecular variants in the GLA gene producing inadequate α-galactosidase A (AGA) activity." (PMID 33335842, 2020). "Fabry disease (FD) results from a deficiency in the exoglycohydrolase, α-galactosidase A (AGA), an enzyme required for the sequential degradation of glycosphingolipids, which consequently accumulate in the lysosomes of affected cells." (PMID 33335842, 2020). "Fabry disease (FD; MIM: 301500) is a lysosomal storage disorder (LSD) with an X-linked inheritance secondary to mutations in the GLA gene (NCBI: NC_000023.11; Xq22), which results in the absent or decreased activity of lysosomal hydrolase α-galactosidase A (AGA, α-GalA; BRENDA: EC3.2.1.22)." (PMID 36982318, 2023).
Areflexia (1 paper, 2017). Absence of neurologic reflexes such as the knee-jerk reaction. "Interestingly, some AGA specificities are associated with the GBS subtypes such as anti‐GM1 is closely related to the AMAN and GQ1b antibody are notably associated with MFS, characterized by ophthalmoplegia, ataxia, and areflexia (van Doorn & Jacobs, 2016; Mori, Kuwabara, & Yuki, 2012)." (PMID 28523231, 2017).
celiac disease (1 paper, 2010). An autoimmune genetic disorder with an unknown pattern of inheritance that primarily affects the digestive tract. "CD antibodies such as IgA AGA or IgG AGA or both were found in 7 patients (11.6%), although did not report symptoms indicative of celiac disease." (PMID 22308135, 2010).
Cerebral atrophy (1 paper, 2022). Atrophy (wasting, decrease in size of cells or tissue) affecting the cerebrum. "We demonstrated cognitive deficits and brain imaging findings (i.e., thalamic T2 hypointensity, cerebral atrophy) similar to those previously published in the Finnish AGU population, suggesting loss of the AGA enzyme activity, regardless of genotype, leads to similar patterns of neurodegeneration." (PMID 36101820, 2022).
colon cancer (1 paper, 2023). "The results from the MTT assay showed that AGA inhibited cell viability of all colon cancer cells in a dose-dependent manner with an IC50 value of 10 mg/ml at 72 h." (PMID 36597025, 2023). "Next, we explored the mechanism of AGA-mediated inhibition of SW620, SW480, and HT29 colon cancer cell growth." (PMID 36597025, 2023).
KID syndrome (1 paper, 2018). Keratitis (and hystrix-like) ichthyosis deafness (KID/HID) syndrome is a rare congenital ectodermal disorder characterized by vascularizing keratitis, hyperkeratotic skin lesions and hearing loss. "As is true for the many characterized cell lines from KID syndrome patients, in the present study, cells with Cx26 constructs with the mutation Cx26-D50N showed increased uptake of NB fluorescent dye, and the increased uptake was abolished by the hemichannel blockers CBX and AGA." (PMID 30150638, 2018).
Lysosomal disease (1 paper, 2021). "Arylsulphatase G (ARSG) and aspartylglucosaminidase (AGA), lysosomal enzymes, which are mutated in lysosomal diseases both in animals and humans, were also downregulated." (PMID 34831346, 2021).
mental retardation (1 paper, 2018). "The most statistically significant association with candidate genes, AGA, DYRK1A, SETD4, and TTC3, was found in mental retardation (adjP = 0.0014)." (PMID 29739397, 2018).
oral cancer (1 paper, 2020). "Therefore, AGA holds a great potential to be an oral cancer treatment strategy." (PMID 33142749, 2020).
retinal diseases (1 paper, 2004). "In many instances, this results in a significant reduction of genes in the respective intervals offering a manageable number of candidates for retinal diseases (e.g. the RP29 locus contains 28 SGPs of which 5 are present in the reference retinome including GPM6A, WDR17, FLJ22649, VEGFC, AGA)." (PMID 15283859, 2004).
Rett/Rett-like syndrome (1 paper, 2025). "The WES initially focused on the analysis of 37 genes involved in Rett/Rett-like syndrome (characterized by episodes of developmental regression) and the AGA gene involved in AGU, but no pathogenic or likely pathogenic variants were discovered." (PMID 40643555, 2025).
schizophrenia (1 paper, 2017). A major psychotic disorder characterized by abnormalities in the perception or expression of reality. "Spearman’s correlations between magnetic resonance spectroscopy measures and AGA IgG in schizophrenia patients." (PMID 28674504, 2017).
tendinopathy (1 paper, 2020). "Therefore, we expect that optimal amounts of AGA and T0070907 can prevent tendinopathy by inhibiting this aberrant differentiation." (PMID 32294907, 2020). "In addition, AGA and T0070907 may play important roles in the treatment of tendinopathy." (PMID 32294907, 2020).
cancer (2 papers, 2016 to 2020). A tumor composed of atypical neoplastic, often pleomorphic cells that invade other tissues. "Mechanistically, AGA suppressed all EMT markers; consequently, it decreased the migration ability of cancer cells." (PMID 33142749, 2020). "Interestingly, both AGA and ASRGL1, related to N4-(beta-N-acetylglucosaminyl)-L-asparaginase activity, are highly connected in the reconstructed network, which may provide clues as to how these two genes interact with other cancer genes." (PMID 27830726, 2016).
infection (2 papers, 2017 to 2023). The state of being infected such as from the introduction of a foreign agent such as serum, vaccine, antigenic substance or organism. "Numerous types of infection were closely related to GBS, mainly including Campylobacter jejuni, Cytomegalovirus, which may lead to the production of anti‐gangliosides antibodies (AGA)." (PMID 28523231, 2017).
tumor (1 paper, 2023). "Taken together, these results demonstrated its in vivo anti-tumor effect, and also excluded the concerns of adverse events caused by AGA therapy." (PMID 36597025, 2023).
AGA also shares sentences with these, for which no sentence is quoted: psoriasis (2 papers); aminoacylase 1 deficiency (1); Ataxia (1); autosomal recessive inherited disorder (1); cognitive deficits (1); dengue (1); dermatomyositis (1); dimethylglycine dehydrogenase deficiency (1); Gaucher disease (1); hyperprolinemia type 1 (1); metabolic disorders (1); Norrie disease (1); ophthalmoplegia (1); pancreatic insufficiency (1); Parkinson disease (1); psychological distress (1).